VIM (vimentin)
Diseases named in the same sentence as VIM in open-access papers (continued):
Sharing a sentence is not in itself a finding about the gene and the disease.
infection (continued). "Whereas the role of InlF during infection of choroid plexus epithelial cells has not been investigated before, InlF was implicated as a key listerial factor in interaction with vimentin during invasion of Lm into the brain microvascular endothelial cell line hCMEC/D3." (PMID 36361697, 2022). "However, treatment of VACV‐infected vimentin‐null cells with acrylamide still blocked infection." (PMID 33792166, 2021). "Furthermore, decreased expression of transcriptional factor (SNAI1, SNAI2) during pathogen infection may suppress VIM expression and reduce pathogen translocation into the cells." (PMID 34372621, 2021). "Moreover, it has been suggested that vimentin and myofibrils (in cardiomyocytes) might be weakened by intracellular infection." (PMID 34154418, 2021). "However, we have shown that extracellular vimentin influences a range of cellular functions and might become an important player in the treatment of diseases or the prevention of particular infections." (PMID 34299089, 2021). "This led us to investigate whether vimentin is recruited to the CCV during infection." (PMID 33282747, 2020). "Thus, vimentin provides a stabilizing scaffold for C. trachomatis inclusions during infection." (PMID 33282747, 2020). "Besides, one previous study demonstrated that the tail region of surface vimentin was the endothelial target for Cowpea mosaic virus (CPMV) during infection, supporting the hypothesis that vimentin is functionally important in the viral pathogenesis." (PMID 26801988, 2016). "Thus, the function of superficial vimentin in infection process of a pathogen must be investigated." (PMID 27910934, 2016). "Given that vimentin immunolabeling was more pronounced in A. phagocytophilum infected versus uninfected cells, we rationalized that vimentin expression might be upregulated during infection." (PMID 29056733, 2016). "Interestingly, the expression of vimentin was found to show an upregulating tendency both in H37Rv and H37Ra infections when the MOI was 5 bacilli/macrophage, which indicates that there is a need for a threshold number of organisms for eliciting a pathogen specific response." (PMID 26876331, 2016). "For instance, infection with African swine fever virus (ASFV) can lead to the rearrangement of vimentin into a cage surrounding a virus factory, which may prevent movement of viral components into the cytoplasm and concentrate late structural proteins at sites of virus assembly." (PMID 22463732, 2012). "Whether other types of IF are required for viral entry in clinically-relevant cells like epithelial cells and neurons, and whether the presence of intact vimentin networks is also necessary for infection with other herpesviruses besides CMV remains to be determined." (PMID 21994768, 2011). "During infection, vimentin colocalizes with the NS1 protein and rearranges into a cage-like defense structure; vimentin overexpression inhibits viral replication, while its silencing promotes the replication, indicating a dual regulatory role." (PMID 41516263, 2025). "Teo and Chu observed dynamic changes in NS4A-vimentin colocalization during DENV2 infection, with colocalization increasing as the infection progressed and peaking at 48 h postinfection." (PMID 41516263, 2025). "Here, we demonstrated that vimentin, a host intermediate filaments protein, is dispensable for HCV infection in cell models but essential for simulated in vivo infection in differentiated hepatocytes." (PMID 39611409, 2025). "Conversely, in vitro infection of cervical cells with Nippostrongylus brasiliensis led to reductions in the uptake of HPV16 pseudo-virions, cell migration, and expression of vimentin and N-cadherin." (PMID 39851470, 2025). "After SS2 infection, co-localization of RPSA and VIM dramatically increased, particularly where bulges were observed; these were in contrast to uninfected cells (red arrow)." (PMID 38331785, 2024).
infection (continued). "We found that after 72 hours post-infection, SARS-CoV-2 spike protein and VIM co-localized in SARS-CoV-2 infected primary human differentiated nasal epithelial cells grown at the air-liquid interface, with an R2 value of 0.47." (PMID 38007005, 2024). "Thus, we hypothesize that IGHG1 and LGALS1, detected early in E. granulosus infection, induce EMT initiation in the host liver cells; this results in vimentin expression in the middle infection stage, followed by persistent increases in expression in the late infection stage." (PMID 39625960, 2024). "Upon infection of cells with JEV, the vimentin-Fc fusion protein binds to the virus, effectively preventing its attachment to receptor sites on target cell membranes and impeding random virus internalization." (PMID 38500602, 2024). "Upon infection, FLAG-tagged SopB was secreted into host cells and displayed intimate co-localization with endogenous vimentin." (PMID 36717589, 2023). "To further elucidate vimentin’s role in activating NF-κB, we compared the effect of SS2 infection on the phosphorylation level of NF-κB protein p65 in STEC and VIM KO STEC." (PMID 36717839, 2023). "Upon damage or infection, intracellular MIF can also interact with nitrogen permease regulator-like 3 (NLRP3) to facilitate the interaction between NLRP3 and vimentin, resulting in the release of IL1β." (PMID 38052787, 2023). "This is the case for infection with bluetongue virus, whose capsid viral protein 2 (VP2) binds directly to cytosolic vimentin." (PMID 37475865, 2023). "Vimentin can be bound by the spike (S) protein and serve as a cellular coreceptor for SARS-CoV during infection, thereby promoting the adsorption and entry of SARS-CoV." (PMID 37848995, 2023). "Vimentin knockdown U251 cells (VIM-KD) and wild type U251 cells (VIM-WT) were harvested after two hours and twenty-four hours EV71 post-infection." (PMID 35807435, 2022). "Vimentin, a cytoskeletal component involved in DENV infection, is significantly reorganized during infection." (PMID 35433510, 2022). "Together, these data suggest that vimentin is indispensable for SS2 translocation across the tracheal epithelium and for the occurrence of invasive infection." (PMID 35921364, 2022). "Seven infection/inflammation-related proteins in our assay, S100A9, VIM, LGALS1, APCS, MMP9, LDHA, and CRP, were elevated in TB-PEs and the other-infectious-PEs." (PMID 35197508, 2022). "With its ability to collapse vimentin filaments well documented, we proceeded to evaluate the impact of acrylamide treatment on VACV infection." (PMID 33792166, 2021). "At the end of the 4th day of infection, the CK19 expression levels reduced to (0.5 ± 0.09) folds while vimentin expression levels increased up to (4 ± 0.6) folds." (PMID 33093503, 2020). "The anti-vimentin antibody and an anti-SCARB2 antibody had an additive effect on inhibition of EV-A71 infection." (PMID 31924205, 2020). "The expression of the EMT markers Vimentin, ZEB1, and Snail, as well as the induction of the “hummingbird” phenotype after 24 h of infection, were also CagA-dependent, as previously reported." (PMID 32545795, 2020). "Vimentin would support CHIKV replication, as confirmed by inhibition of infection following silencing of its expression (siRNA)." (PMID 32516914, 2020). "During the four days following the infection, the CK19 and the vimentin transcription levels have changed significantly at p ≤ 0.001, with respect to both MOI and duration of infection, separately." (PMID 33093503, 2020). "Infection of MFT-16 cells, which lack vimentin, resulted in a >2-fold decrease in intracellular bacteria compared to infection of vimentin-expressing MFT-6 cells." (PMID 29487235, 2018). "Two proteins were inversely regulated after infection with the attenuated E75CV1 strain: HSPA1B and vimentin." (PMID 30208957, 2018).
infection (continued). "In order to study any functional involvement of vimentin for infectious HPV internalization, we preincubated both untreated and FPC HPV16-PsVs with soluble human recombinant vimentin protein before infection." (PMID 28566373, 2017). "Cluster of differentiation CD163, vimentin (VIM), and nmII as well as detected proteins are assessed together by string analysis, which elucidated a potentially different infection mechanism." (PMID 29052333, 2017). "Surprisingly, no significant change in the expression level of superficial vimentin on VECs was observed at 15, 38, and 62 h post-DENV-2 infection (hpi) compared with that at 0 h of infection." (PMID 27910934, 2016). "DENV EDIII directly interacts with the rod domain of vimentin on the VEC surface and thus mediates the infection." (PMID 27910934, 2016). "On the contrary, the mesenchymal molecules, Vimentin and N-cadherin were sharply increased after Ad5-HIF-1α-EGFP infection." (PMID 26057751, 2015). "Unexpectedly, the assembled VP4 did not overlap with cytoskeletal proteins F-actin, beta tubulin or vimentin in either IBDV-infected cells or wtVP4-transfected DF-1 cells at 24 and 36 h after infection or transfection." (PMID 26440769, 2015). "In response to infection or injuries, the activation of astrocytes can be characterized by their upregulation of intermediate filaments, such as GFAP, vimentin." (PMID 23144903, 2012). "When tested during infection, LEHD-fmk and DEVD-fmk were inactive in inhibiting CPAF-mediated cleavage of vimentin or bacterial growth." (PMID 21990969, 2011). "Onset of infection was also delayed (AD169), and both delayed and reduced (TB40/E), by vimentin bundling in fibroblasts from patients with giant axonal neuropathy." (PMID 21994768, 2011). "Previously, we observed that both vimentin and microtubule were reorganized in DV2 infection, and role for actin in the release of WNV has been reported by others." (PMID 20824170, 2010). "Interestingly, levels of PKC and Rho-kinase remain unchanged during infection, contrasting with CSFV, which relies heavily on the RhoA/ROCK pathway for vimentin rearrangement." (PMID 41516263, 2025). "Considering that vimentin does not affect HCV cell‐free infection, we employed a strategy of using anti‐E2 nAb in combination with anti‐vimentin Ab to evaluate their impact on HCV cell–cell transmission, to exclude the influence of cell‐free virus." (PMID 39611409, 2025). "Although cell surface receptors, such as fibronectin and integrins, are known to play a role in the intracellular infection of S. aureus, the function of vimentin has not yet been reported." (PMID 40061451, 2025). "In this study, we demonstrated that vimentin is critical for HCV cell–cell transmission but not cell‐free infection, both in vitro and in a simulated in vivo model." (PMID 39611409, 2025). "Furthermore, the expression levels of the epithelial marker E-cadherin and the mesenchymal marker Vimentin in MDA-MB-231 and MCF-7 infection models were analyzed through Western blot analysis and RT-qPCR." (PMID 40589632, 2025). "Supporting this concept, EV71 binds vimentin and its primary receptor SCARB2 at distinct cell sites, with vimentin acting not as a competitor but as an attachment factor that facilitates infection by presenting the virus to its functional receptor." (PMID 41516263, 2025). "The percentage of Her2+ cells expressing vimentin was not significantly affected early after infection (3–6 dpi)." (PMID 38645169, 2024). "Infection with RV induces substantial restructuring of vimentin in adherent kidney cells, whereas such reorganization is not observed in differentiated human intestinal epithelial cells." (PMID 38793550, 2024). "However, the phosphorylation levels of vimentin, vinculin, paxillin, and LIM domain kinase 1 were upregulated at 6 h and 36 h after infection." (PMID 38759153, 2024).
infection (continued). "The results show that the total protein level of vimentin and the transcription of the vimentin gene did not change at all time points during infection (1–4 hpi)." (PMID 36717839, 2023). "Vimentin still aggregated around SCV post ΔsipB or ΔphoP strain infection, indicating that they are not able to trigger vimentin-dependent replication." (PMID 36717589, 2023). "Recently, extracellular vimentin expressed and released by endothelial cells was shown to act as an adjuvant to ACE-2, increasing ACE-2-mediated entry of SARS-CoV-2 into the endothelium and thereby promoting infection." (PMID 36741194, 2023). "During the process of infection of Vero E6 cells by severe acute respiratory syndrome coronavirus (SARS-CoV), vimentin was involved in the virus’s entry into cells through direct interaction with the viral spike protein in a spike-ACE2 (angiotensin-converting enzyme 2) complex." (PMID 36912679, 2023). "Activation of astrocytes is expected to occur in the presence of WNV, and this was observed in the BSCs following WNV infection because GFAP, VIM, LCN2, and STEAP4 all showed enhanced expression following infection with WNV compared with the mock-infected samples." (PMID 35412380, 2022). "Moreover, it is necessary to show the localization of vimentin and RHDV molecules in tissues during various infections to confirm or deny the presence of RHDV molecules in the cells after mesenchymal transition and to show host–pathogen interactions." (PMID 34372621, 2021). "The first is the lack of data from the vimentin expression in tissues in several time points post-infection." (PMID 34372621, 2021). "Paradoxically, depolymerization of the filamentous vimentin in the case of inflammation can loosen the intercellular junctions and increase BBB permeability, while the surface vimentin may also help infection." (PMID 34198868, 2021). "This suggests that the cellular machinery recognizing foreign dsRNA does not trigger the events leading to vimentin dynamics during infection." (PMID 31619557, 2020). "At 24 and 48 h post-infection, the absence of vimentin did not seem to influence bacterial replication." (PMID 33282747, 2020). "In the case of infection by foot-and-mouth disease virus, vimentin interacts with non-structural protein 3A and exerts complex effects in viral replication and yield." (PMID 32630064, 2020). "Vimentin is also important for efficient infection by HIV, through mechanisms that are not yet well understood." (PMID 32630064, 2020). "On the contrary, no inhibition of infection was noted in SH-SY5Y cells when treated with anti-VIM antibody or in U-87 MG cells when treated with anti-PHB1/2 antibodies." (PMID 32306962, 2020). "Infection by the Moloney mouse sarcoma virus was also found to induce vimentin cleavage resulting in a fragment lacking all or part of the C-terminal tail." (PMID 32630064, 2020). "In the present study, a similar number of cells expressed vimentin regardless of the infection status." (PMID 32627957, 2020). "Altogether these results show that vimentin dynamics, taking place in the infected cells, regulate nonstructural protein synthesis without compromising infection efficiency but affecting host cell survival." (PMID 31619557, 2020). "The results suggest that the vimentin dynamics regulate viral nonstructural protein synthesis while having less effect on structural protein synthesis or overall infection efficiency." (PMID 31619557, 2020). "Following infection, cells were fixed but not permeabilized to permit labeling of only extracellular bacteria and surface expressed vimentin." (PMID 31181121, 2019). "VP1 increased the expression of vimentin, suggesting that EV71 may amplify the infection with the increase in the virus receptor." (PMID 31285854, 2019). "We detected WT levels of CPAF-mediated vimentin cleavage with the S49A and Y117L mutants, indicating that the phenotypes we observe are not due to differential vimentin cleavage during infection." (PMID 29513221, 2018).
infection (continued). "The results showed a significantly suppression of epithelial marker genes E-cadherin, collagen IV and cytokeratin, as well as increased expression of mesenchymal marker genes N-cadherin, snail, vimentin and S100A4 at 12 h after infection with SH0165 (108 CFU/mL)." (PMID 30258822, 2018). "Collectively, these results demonstrate a role for surface vimentin in L. monocytogenes invasion of host cells, including cell types relevant to infection of the BBB and brain, and suggest that InlF mediates invasion of host cells through an interaction with surface-localized vimentin." (PMID 29487235, 2018). "For all three prion strains Vimentin and Cx3cr did not increase at these same early time-points of infection, suggesting that these genes were not markers of glial activation in these prion models." (PMID 27046083, 2016). "We propose that the superficial vimentin could be a novel molecule involved in DENV binding and infection of VECs." (PMID 27910934, 2016). "Given that the vimentin assembled around ApVs was likely in the insoluble form and thus would be insensitive to WFA, we examined the effects of treating host cells with the inhibitor prior to and during infection." (PMID 29056733, 2016). "Uninfected cells served as a control to examine if vimentin is modified by SUMO-2/3 in the absence of infection." (PMID 29056733, 2016). "Immunehistochemical staining showed that vimentin expression was increased by E44 infection but not by ZD1 (the IbeA deletion mutant) in the brain cortex of wildtype mice, while there was no vimentin staining seen in vimentin knockout mice." (PMID 27657497, 2016). "Further studies on vimentin and potential involvement of the other cytoskeletal components during infection have not been explored." (PMID 29056733, 2016). "Vimentin and SUMO-2/3 heavily label and colocalize at the ApV throughout infection." (PMID 29056733, 2016). "Skin biopsies of the SC inoculation site obtained seven days after infection with either UCD52 or UCD59 are noted for prominent neutrophilic infiltration with extensive infection of endothelial cells (CD31-positive), fibroblasts (vimentin-positive), and macrophages (CD68-positive)." (PMID 24681748, 2014). "Finally, at 24 hrs post-infection, all the markers were up-regulated: the pri-miR-200b and ZEB1, along with IL-8, by both wt and the CagA-deleted strain, E-cadherin and vimentin by the wt bacteria only." (PMID 23565224, 2013). "Remarkably, infection of old VSMC with an adenovirus harboring CAST indeed inhibits calpain-1 activity and generates a pattern of proteolytic products of vimentin resembling that from the untreated young cells (30 mo)." (PMID 18493299, 2008). "Furthermore, studies on both RV and MRV have shown that their infection disrupts and reorganizes vimentin filaments without affecting MTs or microfilament bundles." (PMID 38793550, 2024). "Irrespective of the FPV infection status, all tumors except one corresponded to high-grade, invasive lesions and concurrently expressed epithelial (keratins, E-cadherin, β-catenin) and mesenchymal (vimentin, N-cadherin, CD146) proteins." (PMID 38003753, 2023). "Given that vimentin shrinking was evident after 12 hpi, we speculated that vimentin does not participate in the early phase of infection." (PMID 36717589, 2023). "Perhaps, the putative mediator CD151, integrin and vimentin expressed in non-infected PGE may be associated with PRRSV viral entry and host response during the early stage of infection." (PMID 37099541, 2023). "After CHIKV infection, the distance between the outermost layer of vimentin protein and the edge of the nucleus in Hela cells in “DMSO” group was significantly reduced compared with that in “control” group which became more obvious as the infection time increased." (PMID 37928675, 2023). "This interesting finding suggests that vimentin may not function as a coreceptor during NDV infection but instead may influence the infection process following viral attachment." (PMID 37848995, 2023).